CD44 (CD44 molecule (IN blood group))
Diseases named in the same sentence as CD44 in open-access papers (continued):
Sharing a sentence is not in itself a finding about the gene and the disease.
tumor (continued). "There are a number of reports correlating the expression of CD44 variants in metastatic spread, and their therapeutic targeting for tumour control." (PMID 23457460, 2013). "In previous studies, overexpression of CD44 was associated with tumor invasion, metastasis, and drug resistance." (PMID 23803658, 2013). "Additional transmembrane proteins such as CD44 and EpCAM have been associated with tumour-initiating frequency and are abundantly expressed in TICs of numerous tumour entities." (PMID 23150174, 2013). "CD44 is a cell-adhesion molecule which is expressed by macrophages, and has been previously reported to be up-regulated in tumor-associated macrophages, playing a role in their recruitment and activation." (PMID 24098347, 2013). "Conversely, most data on CD44 alternative splicing in neoplasia and tumour progression have focused on the associations of the expression of single CD44 variable exons." (PMID 23342032, 2013). "Most of the literature agrees that ‘CD44’ plays an important role during tumour progression based on ‘overexpression’ of specific variant regions containing isoforms at mRNA and/or protein level." (PMID 23151220, 2012). "We mined public transcriptomics databases for gene expression data on CD44, and analyzed normal, immortalized and tumour-derived human cell lines for splice variants of CD44 at both the transcript and protein levels." (PMID 22242150, 2012). "The second hallmark report established that miR-373 and miR-520c can also promote tumor invasion and metastasis by regulating the cell-surface glycoprotein encoding gene CD44 (cell surface receptor for hyaluronan)." (PMID 22408395, 2012). "We previously analysed the same group of OSCC primary samples, and found high levels of CD44 and its v6 variant, which was particularly expressed in high-grade tumours." (PMID 22882088, 2012). "And CD44(v6), a splice variant of the CD44, is a transmembrane glycoprotein associated with cell adhesion and has mostly been investigated in tumours." (PMID 22007253, 2012). "Clinically, several CD44 isoforms have been identified as potential metastatic determinants as a result of an association between their expression and extent of tumour spread and disease stage." (PMID 23039365, 2012). "CD44 expression was linked with low-grade tumours (P=0.02), while there was a trend for CD24 to associate with advanced T-stage (P=0.08)." (PMID 22333601, 2012). "Similar to univariate analysis, after adjustment, amplification of ERBB4 (OR = 2.95, 95% CI = 1.27–6.86, P < 0.05) and CD44 (OR = 2.49, 95% CI = 1.08–5.79, P < 0.05) remained significantly associated with poor tumor differentiation." (PMID 22606006, 2012). "In some tumor studies, hyaluronan binding to tumor cells promoted Nanog protein in association with CD44 followed by Nanog activation and the expression of pluripotent stem cell regulators such as Rex1 and Sox2." (PMID 22400115, 2012). "Particular CD44 variant isoforms seem to act as “metastasis genes” via tumour microenvironment-driven shifts in v3 and v6 expressions." (PMID 23151220, 2012). "Another possibility is that CD147-KD induced inhibition of angiogenesis leads to a secondary CD44-associated effect of tumor vasculature." (PMID 22870202, 2012). "The expression of certain CD44 variants is reported to be closely associated with tumor progression, and this varies depending on tumor type studied." (PMID 22870202, 2012). "The association between the proportions of CD44+/CD24- tumor cells and the clinico-pathological features of these patients was evaluated." (PMID 22762532, 2012). "A rather unexpected finding was that CD44 positivity was significantly linked with well-differentiated tumours." (PMID 22333601, 2012). "Loosely packed or dispersed tumor cells associated with areas of cell death were apparent in both PC-3M-luc-CD44-KD and PC-3M-luc-CD147-KD xenografts." (PMID 22870202, 2012).
tumor (continued). "In our murine system, Snail1 inhibition resulted in loss of tumor-sphere formation, decreased expression of CD44 and Nanog, and decreased tumor growth." (PMID 21929801, 2011). "The altered biological characteristics of these cells indicated that CD44 knockdown changed the stem cell phenotype with high tumor-causing potential into cells with lower tumor-causing potential, representing differentiation of the cancer stem cells." (PMID 22152097, 2011). "Inhibition of Snail1 causes the down-regulation of Nanog, Bmi-1 and CD44, loss of a migration and self-renewal as evidenced by decreased tumor-sphere formation." (PMID 21929801, 2011). "The expression of different CD44 isoforms was significantly associated to certain patient and tumor characteristics." (PMID 21957977, 2011). "In contrast to ER+ disease, the CD44+CD24-/low phenotype was associated with higher tumour grade in ER- cases with 76% of positive tumours being grade 3 compared to 66% of negative cases (P = 0.020)." (PMID 22112299, 2011). "Loss of BRCA1 expression is a marker of tumour aggressiveness and correlates with CD44+ tumour cell phenotype." (PMID 23508738, 2011). "CD44v6 is an isoform of the type 1 transmembrane glycoprotein CD44 generated by alternative splicing and has been implicated in cell adhesion and signaling, growth factor and cytokine presentation, as well as tumor dissemination." (PMID 22182738, 2011). "In ER+ disease CD44+CD24-/low positive tumours were associated with ductal morphology with 81% of CD44+CD24-/low positive cases being ductal compared to 73% of CD44+CD24-/low negative cases (P = 0.012)." (PMID 22112299, 2011). "The tumor-causing potential was reduced in the CD44 knockdown BCSCs, with doses of 104 cells causing tumors in 0% of mice, compared with 100% of mice before CD44 down-regulation." (PMID 22152097, 2011). "The tumor-causing potential of the cells was evaluated to assess the differentiated phenotype after CD44 knockdown." (PMID 22152097, 2011). "We also found that tumours enriched for the CD44+CD24-/low phenotype were associated with the basal-like subtype and with negative lymph node status." (PMID 22112299, 2011). "CD44 has been shown to associate with membrane-associated metalloprotease that cleaves CD44 to produce a modified ectodomain that can enhance tumor cell migration." (PMID 24212937, 2011). "Since the discovery of the high capacity of generating new tumor cells by mammary CD44+CD24-/low cells, this phenotype are associated with worse survival and aggressive behavior." (PMID 21824412, 2011). "In our previous study, it was shown that expression of the CD44 standard form, variant 3, and variant 6 was reduced in UC-associated neoplasia compared to their sporadic counterparts." (PMID 21473743, 2011). "Blocking BMP signaling in this cell population led to benign hair follicle-derived neoplasias resembling human trichofolliculomas, associated with down-regulation of E-cadherin expression and dynamic regulation of CD44." (PMID 22168923, 2011). "An association between CD44+/CD24- frequency and a basal tumor phenotype has already been reported and interestingly we observed an increased frequency of CD44+/CD24- cells in the brain metastases compared to their matched primaries." (PMID 20604919, 2010). "In the current study, the participation of MBDs in the transcriptional repression of the four selected tumour-associated genes CD44, Cyclin D2, GLIPR1 and PTEN was examined." (PMID 20565761, 2010). "It was demonstrated earlier that the full range of CD44 alternatively spliced variants is widely expressed in normal and tumor colonic cells located in the crypt base, known as a colonic stem cell niche." (PMID 20630067, 2010). "CD44 isoform variations in cancer have been associated with the metastatic ability of tumor cells, being involved in numerous processes, including cell proliferation, adhesion and invasion." (PMID 20700505, 2010).
tumor (continued). "It has been suggested that variant forms of CD44, especially CD44v6 which is transiently expressed during embryonic lung development, mediates tumor cell migration and invasion and can suffice for a CSC marker." (PMID 21124918, 2010). "Other proteins identified by at least two glycopeptides as overexpressed on tumour spheres include proteins previously associated with colon CSCs: CD44 and CD166." (PMID 20332776, 2010). "The loss of ERα expression in SP cells or in small transplanted tumours is consistent with this report by Polyak and co-workers who found ERα downregulated in CD44+ compared with CD24+ cells." (PMID 20145614, 2010). "Variant CD44 isoforms are involved in a variety of physiological and pathological processes, among which tumor progression has received most attention." (PMID 20361869, 2010). "Another interesting example is CD44, a multi-functional cell adhesion protein for which many splice variants have been associated with the growth and progression of multiple tumor types." (PMID 20700505, 2010). "The CD44v5 isoform has been identified to enhance tumor cell invasiveness, and tumor cells expressing the CD44v4-10 variant form larger volume primary tumors and more metastases compared to tumors expressing wild-type CD44." (PMID 20700505, 2010). "Contradictory findings have been reported about the association between the expression of CD44, in particular of its v6 splicing variant, and tumour progression." (PMID 20606680, 2010). "Strikingly, the presence of the CD44+/CD24low/- tumor cells was inversely associated with lymph node metastasis (P = 0.019) and tended to be inversely associated with the stage of the disease (P = 0.068)." (PMID 19555472, 2009). "CD44, especially the CD44v6 variant, has a role in tumor progression and metastasis in human cancers." (PMID 19804631, 2009). "The CD44-/CD 24-/low phenotype represents a minor population within primary tumours that is associated with self-renewal and tumourigenic potential." (PMID 18793387, 2008). "CD44 was in the focus of molecular oncology in the early 1990s when it was recognized that variants of it, chiefly CD44v6, regulate tumour progression, invasion, and metastasis formation." (PMID 18852874, 2008). "There are numerous examples of alternatively spliced genes whose products are causally involved in tumour progression, such as CD44, HIF-α, VEGF, osteopontin, and many others." (PMID 18026188, 2008). "The distribution of the CD44 variants is usually restricted, and some variants are only expressed in certain tumor cells where their expression can confer metastatic properties." (PMID 18096084, 2007). "This is supported by other in vitro work that has implicated cell adhesion molecules, such as CD44 and the β1 integrins, in tumour-mesothelial invasion." (PMID 15054468, 2004). "Isoforms of the transmembrane glycoprotein CD44 have been implicated in tumour cell adhesion, tumour differentiation and metastatic spread in various human malignancies." (PMID 9569051, 1998). "The expression of CD44 alternatively spliced variants has been correlated with tumour progression according to Dukes' histological stage." (PMID 8695347, 1996). "In contrast to healthy tissue, tumour samples show a more complex pattern of CD44 expression, indicating a loss of splice control." (PMID 8519665, 1995). "CD44, a cell surface glycoprotein with multiple splice variants, has been implicated in tumor progression, but its compartment-specific roles in PDAC remain unclear." (PMID 41827845, 2026). "Interestingly, CD44hi/CD24hi cells exhibited a mesenchymal-type morphology and expressed higher levels of vimentin, consistent with our finding that CD44/CD24 coexpression in tumor cells was associated with vimentin-positive tumors." (PMID 40647395, 2025).
tumor (continued). "Notably, a memory phenotype (defined by CD62L+CD44+), which is associated with long-term tumor remission after CAR T-cell therapy, was observed exclusively in the PER-treated group, but not in the control group." (PMID 40404658, 2025). "Furthermore, higher CD44 expression is associated with more aggressive behavior, tumor progression, and a worse prognosis for RCC." (PMID 40558504, 2025). "This clinical significance is underscored by the correlation between reduced Sestrin3 expression and diminished patient survival, while Sestrin3 knockout mice develop increased tumor burden with elevated CD133/CD44 expression in diethylnitrosamine/choline-deficient high-fat diet (DEN/CD-HFD) models." (PMID 41438763, 2025). "Therefore, CD44 is a commonly used cancer stem cell (CSC) marker associated with tumor progression and metastasis and promotes epithelial-mesenchymal transition." (PMID 40001633, 2025). "Moreover, CD44 variant isoforms can be helpful for tumor cell targeting (cell therapies) and chemotherapy delivery due to their overexpression in tumor tissue." (PMID 40114966, 2025). "CD44 exists in multiple isoforms arising from alternative splicing, including the standard isoform (CD44s) and various variant isoforms (CD44v), which can exert contrasting effects on tumor progression." (PMID 40805225, 2025). "We further identified that high-RiboSis-activity subpopulations drive microenvironmental immunosuppression via the MIF-(CD74+CD44) axis: CellChat analysis validated this axis promotes myeloid cell polarization toward M2-type tumor-associated macrophages while impairing T-cell activation." (PMID 41394823, 2025). "Moreover, CD44 is a commonly used cancer stem cell marker associated with tumor progression and metastasis." (PMID 40001633, 2025). "Importantly, we also found that high CD44/CD24 coexpression in tumor cells was associated with worse DFS, MFS, and OS." (PMID 40647395, 2025). "Additionally, we observed changes in CD44 expression, another critical marker associated with tumor progression and microenvironmental interaction, which binds hyaluronic acid, an ECM component present in both models." (PMID 40651477, 2025). "Moreover, the results of immunohistochemical analyses of expression profiles of CD44 isoforms/variant exons in tumor samples closely align with TCGA data." (PMID 40114966, 2025). "CD44 is a transmembrane glycoprotein involved in signal transduction between cells and the extracellular matrix and is associated with the invasion, metastasis, and drug resistance as well as the formation of tumor microenvironment in cancers." (PMID 40607003, 2025). "Thanks to these primordial studies, much effort has been focused on detecting CSCs in different tumor tissues, such as the ovary, prostate, lung, pancreas, neck and head, and colon, and many glycoproteins, including CD44, CD133, CD38, CD24, CD34, and CD73, have been linked to stem-like properties." (PMID 37966629, 2025). "Furthermore, alternative splicing of CD44, regulated by splicing factors such as SR proteins, generates CD44s and CD44v isoforms, wherein the latter is often associated with tumor metastasis and chemoresistance." (PMID 40363706, 2025). "Thus, literature suggests that total CD44 and its ligands are linked with autophagy initiation and the stemness properties of tumor cells, thereby promoting resistance to administered therapy." (PMID 40114966, 2025). "In addition, CD44's abnormal expression on the surface of tumor‐associated cells facilitates the upregulation of metastasis, survival, and stemness‐promoting pathways, ultimately resulting in treatment challenges." (PMID 40888184, 2025).
tumor (continued). "Additionally, hsa-miR-199a-3p enhances sensitivity to doxorubicin by modulating CD44, a molecule strongly associated with tumor aggressiveness and drug resistance." (PMID 41154751, 2025). "Moreover, we identified 4 distinct CAF subtypes expressing FAP, that were specifically enriched in regions of tumor-stroma interface and associated with tumor cells and CD44+ macrophages." (PMID 40292277, 2025). "CD44 is associated with tumor initiation, progression, metastasis, and drug resistance." (PMID 41439111, 2025). "In addition, SHMT2 is involved in certain processes of tumorigenesis and development and is associated with the expression of MIF, CD74, CXCR4 and CD44 in the HNSCC tumor microenvironment." (PMID 38625586, 2024). "Finally, a systematic review including nine studies found that CD44-positive was associated with inferior survival, larger tumor size, higher grade and node involvement in TNBC." (PMID 39430073, 2024). "Furthermore, this research demonstrated that CD44 has high expression levels in various cancer cells and tumor-associated macrophages, suggesting that CD44 can act as a key ligand for Siglec-15 within TME." (PMID 39697338, 2024). "Beside the common expression of Pan-Ck, tumor cells were characterized by the expression of markers associated with tumor progression, epithelial-to-mesenchymal transition, and resistance to therapy, such as CD44, S100A4 and CA-IX." (PMID 39575252, 2024). "However, more reliable analyses suggest that increased CD44 expression is linked to aggressive clinical and histopathological features, such as advanced clinical stage, higher histologic grade, and tumor stage." (PMID 38672650, 2024). "CD44 exists in multiple variants due to alternative splicing and it is recognized that different spliced isoforms may contribute differently to tumor progression." (PMID 39201626, 2024). "Its role in promoting tumor growth and metastasis is linked to its ability to interact with cell surface receptors, such as integrins and CD44, which initiate signaling pathways that lead to the proliferation and survival of cancer cells, as well as their movement and invasion." (PMID 38707175, 2024). "However, the complexity of the problem stems from the poorly explained dualistic nature of CD44, which was found to be implicated in both tumor suppression and tumor promotion." (PMID 38255201, 2024). "Certain CD44 variants’ functional roles in tumor growth differ from those of standard CD44s." (PMID 38672650, 2024). "CD44 gene undergoes complex alternative splicing events which generate multiple variants such as CD44v3 and CD44v6 isoforms, which are critically involved in regulating cancer stem cell homeostasis contributing thus to tumor chemioresistance." (PMID 37953485, 2024). "CD44, an adhesion molecule implicated in tumor migration, progression, and metastasis, and CD133, a cell surface glycoprotein of uncertain function but identified in human solid tumors associated with aggressive behavior and metastasis, serve as markers for cancer stem cells (CSCs)." (PMID 38675202, 2024). "This may be attributed to the altered expression of other biological factors associated with CD44 activation and signaling in these two tumor subtypes." (PMID 38796656, 2024). "In the context of glioma progression, CHI3L1 is released into the tumor microenvironment and interacts with CD44 expressed on tumor-associated macrophages, thereby activating the downstream PI3K/Akt signaling pathway and contributing to M2 macrophage polarization." (PMID 39068486, 2024). "Upon MIF/CD74 binding, CD44 is recruited to the receptor complex to initiate Src-family kinase activation, CD44 alternative exon splicing, and expression of tumor-associated isoforms such as CD44v3–v6, which are implicated in enhancing cellular migration, adhesion, and invasion." (PMID 38732068, 2024).